ESR1 (estrogen receptor 1)
Diseases named in the same sentence as ESR1 in open-access papers (continued):
Sharing a sentence is not in itself a finding about the gene and the disease.
ischemic stroke (7 papers, 2012 to 2025). A stroke disorder caused by obstruction of blood flow to the brain, due to thrombotic (local blood clot formation) or embolic (due to a blood clot or other material traveling from another site) event. "However, the drugs that target ESR1 are mainly estrogen, progesterone, selective estrogen receptor modulators, etc., and the main cause of ischemic stroke is due to vascular obstruction." (PMID 35419038, 2022). "SULT1E1 -64G/A, COMT Val158Met, ESR1 c.454−397 T/C and c.454−351 A/G genes were genotyped and compared between cases and controls to identify single nucleotide polymorphisms associated with ischemic stroke susceptibility." (PMID 23112845, 2012). "Considerable studies focusing on ESR1 c.454−397 T/C (rs2234693) and c.454−351 A/G (rs9340799) polymorphisms in intron 1 are most widely discussed, and the studies found that these two SNPs are associated with ischemic stroke, cardiovascular disease, and atherosclerosis." (PMID 23112845, 2012). "The present study was carried out with the aim to determine whether SULT1E1 -64G/A, COMT Val158Met, ESR1 c.454−397 T/C and c.454−351 A/G genes are associated with ischemic stroke of the young and to further explore the gene-gene and gene-environment interactions for young ischemic stroke patients." (PMID 23112845, 2012). "Of these IL-1α, CYP11B2, ESR1 (PVUII), α ADD1, TNF α (G488A), CYP4F2, MDR-1 and t-PA (I/D) were found to be significantly associated with ischemic stroke." (PMID 23505425, 2013). "Genotype and allelic frequencies of the SULT1E1, COMT, and ESR1 genes in ischemic stroke patients and controls and the estimated odds ratio and 95% confidence interval of ischemic stroke risk." (PMID 23112845, 2012). "To determine the ischemic stroke risk contribution of SULT1E1, COMT and ESR1, we examined whether the genotypic and allelic distribution of the gene differed between the 305 cases and 309 controls (301 cases and 308 controls had results of complete 4 SNPs)." (PMID 23112845, 2012). "Although our findings including genotype and haplotype analysis reveal no statistically significant risk for ischemic stroke, a gene-environment interaction effect between ESR1 C-A haplotype and serum estradiol level on young ischemic stroke patients was observed (P for interaction = 0.0348)." (PMID 23112845, 2012). "Using PyMOL software, Discovery studio 4.5 client, and Autodock tools 1.5.6 software, the interaction between potential active compounds (Tanshinol A, Tanshinol B, Tanshinone II A and Przewaquinone C) and ischemic stroke related proteins (MMP2, STAT3, TERT, and ESR1) was studied." (PMID 36133785, 2022). "For further verification, potential core targets (STAT3, MMP2, ESR1, TERT, and MMP9 proteins) for ischemic stroke and core active ingredients (Tanshinol A, Tanshinol B, Tanshinone II A, and Przewaquinone C) for Salvia miltiorrhiza Bge. were further verified by molecular docking." (PMID 36133785, 2022). "However, there are no studies exploring the hormone metabolism and signaling pathway genes together on ischemic stroke, including sulfotransferase family 1E (SULT1E1), catechol-O-methyl-transferase (COMT), and estrogen receptor α (ESR1)." (PMID 23112845, 2012).
Sepsis (7 papers, 2021 to 2025). Sepsis is defined as life-threatening organ dysfunction caused by a dysregulated host response to infection. "In the end, we managed to formulate a signature of 7 IRGs for the prognosis of sepsis patients: − 0.465 × CCL5 + 0.215 × DEFA4 − 1.487 × NFYC + 1.055 × ESR1 − 0.737 × TNFRSF8 − 0.228 × CX3CR1 + 1.003 × SERPINA3." (PMID 36650470, 2023). "GO and KEGG analyses were performed, and the core targets of EGFR, PTGS2, SRC and ESR1 were input into the Omicshare database to identify the possible mechanism by which acacetin affects sepsis." (PMID 34483900, 2021). "Then, network pharmacology screening revealed EGFR, PTGS2, SRC and ESR1 as the top four overlapping targets in a PPI network, and GO and KEGG analyses revealed the top 20 enriched biological processes and signalling pathways associated with the therapeutic effects of acacetin on sepsis." (PMID 34483900, 2021). "All potential targets of acacetin and sepsis were methodically obtained, and the top four overlapping targets in the PPI network were EGFR, PTGS2, SRC and ESR1." (PMID 34483900, 2021). "A PPI network of the 49 common targets between acacetin and sepsis was constructed based on degree value screening, and EGFR, PTGS2, SRC and ESR1 were identified as the core targets." (PMID 34483900, 2021). "Among these 7 IRGs, which could predict the prognosis of sepsis patients, CCL5, DEFA4, ESR1 and CX3CR1 were broadly researched in previous studies." (PMID 36650470, 2023).
ulcerative colitis (7 papers, 2015 to 2025). An inflammatory bowel disease involving the mucosal surface of the large intestine and rectum. "Genetic analysis has revealed that in patients with CD, the c.454-397T allele of the ESR1 gene is more frequent than in patients with ulcerative colitis, but only slightly overrepresented compared to the controls and European population." (PMID 31450614, 2019). "It is important to highlight that while this study has identified targets associated with ulcerative colitis (UC), such as TNF, ESR1, and HSP90AA1, the fundamental pathology of UC is driven by more specific factors and biomarkers." (PMID 40895135, 2025). "In a study of ulcerative colitis, NOB binding to the estrogen receptor 1 (ESR1) inhibited the LPS-induced expression of inflammatory factors in RAW264.7 cells." (PMID 41567632, 2025). "The findings indicated that FS could modulate the progression of ulcerative colitis via multiple targets, with STAT3, EGFR, ESR1, PTGS2, NF-κB1 and JUN identified as the six key targets significantly involved in the pathogenesis and progression of ulcerative colitis." (PMID 40649400, 2025).
adrenocortical cancer (6 papers, 2015 to 2025). "The pathogenesis of the adrenocortical cancer (ACC) involves integration of molecular signals and the interplay of different downstream pathways (i.e. IGFII/IGF1R, β-catenin, Wnt, ESR1)." (PMID 26312764, 2015).
anxiety disorder (6 papers, 2022 to 2025). A category of psychiatric disorders which are characterized by anxious feelings or fear often accompanied by physical symptoms associated with anxiety. "Previous evidences showed that specific ESR1 polymorphisms might contribute to the increased susceptibility to the development of anxiety disorders." (PMID 36386232, 2022).
Azoospermia (6 papers, 2012 to 2025). Absence of any measurable level of sperm,whereby spermatozoa cannot be observed even after centrifugation of the semen pellet. "In contrast, studies have linked ESR1 mutations with both azoospermia and severe oligospermia due to different gene defects." (PMID 39932629, 2025).
cardiomyopathy (6 papers, 2013 to 2025). A disease of the heart muscle or myocardium proper. "We identified 135 variably methylated probes (VMPs) from male mice, linked to genes such as Esr1 and enriched in cardiomyopathy-related pathways." (PMID 41446098, 2025). "In conclusion, the Crif1 conditional knockout mice generated by using the two different cre transgenic lines, Ckmm-cre and Myh6-cre/Esr1, develop cardiomyopathy due to impaired mitochondrial respiration." (PMID 23308255, 2013).
Cirrhosis (6 papers, 2018 to 2023). A chronic disorder of the liver in which liver tissue becomes scarred and is partially replaced by regenerative nodules and fibrotic tissue resulting in loss of liver function. "Botanical drugs and gut microbiota target MAPK1, VEGFA, STAT3, AKT1, RELA, JUN, and ESR1 in the treatment of hepatitis B cirrhosis, and their combined use has shown promise for cirrhosis treatment." (PMID 38029250, 2023). "When controlling for subject sex, differential gene expression of ESR1 remained significantly higher in PoPH female hepatocyte clusters relative to non-PoPH cirrhosis females." (PMID 37558836, 2023). "In particular, BMPR2 expression appeared to be reduced, and both ESR1 and FLT1 expression appeared to be increased, in PoPH peri-central hepatocytes as compared to non-PoPH cirrhosis liver tissue." (PMID 37558836, 2023). "In this study, we observed differential gene expression of BMPR2, ESR1, and FLT1 genes in livers from patients with PoPH relative to non-PoPH cirrhosis, patterns supported by immunohistochemical staining of human liver tissue." (PMID 37558836, 2023). "Differential gene expression analysis showed relative increase in ESR1 gene expression across multiple PoPH cell clusters, as well as decreased BMPR2 expression in PoPH hepatocytes, relative to liver from non-PoPH patients with cirrhosis." (PMID 37558836, 2023). "PoPH samples demonstrated relatively more intense staining for both the ESR1 and FLT1 proteins, and relatively less staining for the BMPR2 protein, in the region surrounding liver central veins (the “peri-central” zone) relative to non-PoPH cirrhosis tissue." (PMID 37558836, 2023). "As PoPH nuclei demonstrated a pattern of differential gene expression involving the BMPR2, ESR1, and FLT1 genes, we then sought to validate this pattern of gene expression using immunohistochemistry staining of human liver tissue from PoPH, non-PoPH cirrhosis, and normal liver tissue samples." (PMID 37558836, 2023).
Crohn disease (6 papers, 2019 to 2024). A gastrointestinal disorder characterized by chronic inflammation involving all layers of the intestinal wall, noncaseating granulomas affecting the intestinal wall and regional lymph nodes, and transmural fibrosis. "The ESR1 gene polymorphism leads to decreased bone mineral density in postmenopausal women and predicts OP occurrence in women with Crohn's disease." (PMID 34239693, 2021). "The different genetic background of CD and UC has already been mentioned, and our observations have led us to hypothesize that c.454-397T allele of the ESR1 gene may associate with Crohn’s disease susceptibility." (PMID 31450614, 2019).
cutaneous melanoma (6 papers, 2016 to 2025). A primary melanoma arising from atypical melanocytes in the skin. "For instance, the higher expression of ESR1 is significantly related with superior OS in head and neck squamous cell carcinoma (HNSC), kidney renal clear cell carcinoma (KIRC), liver hepatocellular carcinoma (LIHC) and skin cutaneous melanoma (SKCM)." (PMID 34322374, 2021).
cyst (6 papers, 2016 to 2026). A sac-like closed membranous structure that may be empty or contain fluid or amorphous material. "On the other hand, in the ectopic endometrium from the cyst walls of ovarian endometriomas, ESR1 mRNA and the expression of protein ERα were attenuated compared with eutopic endometrial tissues and cells, and in contrast, ERβ was upregulated." (PMID 32316608, 2020).
epilepsy (6 papers, 2019 to 2022). A brain disorder characterized by episodes of abnormally increased neuronal discharge resulting in transient episodes of sensory or motor neurological dysfunction, or psychic dysfunction. "The neuroprotective effect of ESR1 mainly manifests in its influence on synaptic plasticity, which explains the role of ESR1 in epilepsy treatment." (PMID 35707480, 2022). "We found that Abrus cantoniensis was mainly connected with epilepsy through the neuroactive ligand-receptor interaction signaling pathway, the neurodegeneration pathway, and multiple disease signaling pathway; the docking between ESR1 and components is the most stable among the core targets." (PMID 35707480, 2022). "In the present study, we demonstrated that PTGS2, ESR1, MAPK1, PTPN11, and MAPK3 may be the targets of linoleic acid against epilepsy." (PMID 36034878, 2022).
head and neck cancer (6 papers, 2018 to 2025). A primary or metastatic malignant neoplasm affecting the head and neck. "FOXA1 and ESR1, two of the top three ranked factors for head and neck cancer (HNSC) have been identified as tumor suppressors." (PMID 33778495, 2021). "Analysis of RNAseq data taken from the TCGA study of 525 patients with primary head and neck cancer showed that patients with higher than median tumor ESR1 expression (ESR1> 5.56) had significantly better survival rates than patients with lower tumor ESR1 expression." (PMID 32144339, 2020). "Second, third ranked ESR1 has been hypothesized to have tumor suppressive function in laryngeal squamous cell carcinoma (LSCC), another subcategory of head and neck cancer." (PMID 33778495, 2021).
Hepatitis (6 papers, 2012 to 2023). Inflammation of the liver. "As a nuclear receptor family, ESR1 is a ligand-activated transcriptional regulator of metabolic processes, including lipid metabolism, bile acid homeostasis, energy expenditure, and hepatitis." (PMID 36506575, 2022). "Meanwhile, we observed that in hepatitis-related HCC, patients with higher expression of BCL2L1, EGFR, ESR1, HNF4A, MAPK8, and PTEN, and lower expression of HDAC1 had a better clinical prognosis." (PMID 36133813, 2022).
laryngeal carcinoma (6 papers, 2016 to 2025). Carcinoma that arises from the laryngeal epithelium. "In another study, a higher level of both ESR1 and ERα was observed in laryngeal cancer samples." (PMID 38672656, 2024). "Aberrant methylation of the ESR1 gene, a ligand‐activated transcription factor located on chromosome 6q24‐q27 that is composed of several domains important for hormone and DNA binding and for transcription activation, has been found to be an independent marker of poorer outcome in laryngeal cancer." (PMID 27367901, 2016).
mucinous ovarian cancer (6 papers, 2011 to 2025). An invasive malignant neoplasm that arises from the ovary and is characterized by the presence of malignant epithelial cells that contain intracytoplasmic mucin and may resemble the epithelial cells of the endocervix or gastrointestinal tract. "Serous, endometrioid, and mucinous ovarian cancers were almost always positive for either ESR1 or GREB1, suggesting a possible reliance on signalling through ESR1 and/or GREB1." (PMID 29973689, 2018). "In addition to identifying genes previously known to be involved in these tumors, we identified alterations in RAD51C, NOTCH4, SMARCA1/4, and JAK1 in ovarian endometrioid, ESR1 in uterine endometrioid, and SMARCA4 in ovarian mucinous carcinomas." (PMID 40981433, 2025).
nasopharyngeal carcinoma (6 papers, 2018 to 2023). A carcinoma arising from the nasopharyngeal epithelium. "The estrogen receptor-1 protein ESR1 (upregulated), is known to induce the expression of the immediate-early viral gene BZLF1 and has been also associated to poor prognosis of nasopharyngeal carcinoma." (PMID 38077135, 2023). "Two core networks were generated by hub gene screening using the MCODE plugin of Cytoscape, and AKT1, CTNNB1, HSP90AA1, ESR1, CCND1, and EGFR were identified as key hub proteins, which may play an important role in the efficacy of icaritin in the treatment of nasopharyngeal carcinoma." (PMID 36467051, 2022).
oral squamous cell carcinoma (6 papers, 2016 to 2025). "ESR1 is found in only a small percentage of older males with oral squamous cell carcinoma, whereas young females generally do not express ESR1 or the progesterone receptor; however, ESR2 is predominantly expressed in tissue samples from patients with oral cancer." (PMID 39684286, 2024).
Osteopenia (6 papers, 2010 to 2025). Osteopenia is a term to define bone density that is not normal but also not as low as osteoporosis. "Moreover, conditional deletion of estrogen receptor α (ESR1) in skeletal muscle leads to osteopenia by increasing the ratio of osteoclast surface to the bone surface." (PMID 41019997, 2025).
periodontitis (6 papers, 2014 to 2025). An acute or chronic inflammatory process that affects the tissues that surround and support the teeth. "Recent evidence highlights several molecular mediators involved in the pathogenesis of periodontitis namely estrogen receptor 1 (ESR1), matrix metalloproteinases (MMP2, MMP9, MMP13), and signal transducer and activator of transcription 1 (STAT1)." (PMID 41009706, 2025). "The high binding affinity of EGCG for ESR1 is particularly noteworthy, as ESR1 plays a role in bone homeostasis and inflammation, both of which are critical in periodontitis progression." (PMID 41009706, 2025). "The identification of ESR1 as a potential therapeutic target further highlights the possible involvement of estrogen receptor signaling in the pathogenesis of periodontitis and suggests that EGCG may have broader implications beyond its antioxidant and anti-inflammatory properties." (PMID 41009706, 2025). "Protein–protein interaction (PPI) network analysis identified ESR1, MMP2, MMP9, MMP13, and STAT1 as hub genes, highlighting their central role in EGCG-mediated modulation of periodontitis." (PMID 41009706, 2025). "By integrating these results with Gene Ontology, pathway, and disease enrichment analyses, it was determined that ESR1, MMP2, MMP9, MMP13, and STAT1 are potential key targets of EGCG in the context of periodontitis treatment." (PMID 41009706, 2025). "In contrast, 8 MRs (ESR1, CEBPB, FOS, BCL6, E2F1, SPI1, STAT3, and ETS1) were consistently expressed at higher levels (U test statistic between 10 and 16) in the periodontitis condition." (PMID 37834287, 2023). "The strong interactions of EGCG with ESR1, MMP2, MMP9, MMP13, and STAT1 support its potential to modulate MMP activity and reduce extracellular matrix degradation, thereby mitigating tissue destruction in periodontitis." (PMID 41009706, 2025).
uterine tumors (6 papers, 2014 to 2025). "Interestingly, both GREB1- and ESR1-rearrangement have been described in uterine tumors other than UTROSCTs, namely adenosarcoma and leiomyosarcoma." (PMID 40150134, 2025). "First, GREB1-rearranged uterine tumours as a group displayed a greater degree of genomic complexity with more extensive copy number alterations than conventional UTROSCTs, including those harbouring ESR1::NCOA2/3." (PMID 41424301, 2025).
Venous thrombosis (6 papers, 2009 to 2023). Formation of a blood clot (thrombus) inside a vein, causing the obstruction of blood flow. "ESR1 genotype is a predictor of complex lesions, of coronary thrombosis, and has a role in rising HDL cholesterol level." (PMID 19134193, 2009).
carcinosarcoma (5 papers, 2012 to 2024). A malignant tumor composed of a mixture of carcinomatous and sarcomatous elements. "Carcinosarcomas had targetable mutations in AKT2 and harbored a resistance mutation in ESR1." (PMID 28424409, 2017).
cholestasis (5 papers, 2011 to 2024). Impairment of the bile flow caused by obstruction within the liver, or outside the liver in the bile duct system. "ESR1 and HNF alpha were linked in Figure S3A6 and both are involved in hepatic cholestasis, indeed EE2-induced hepatotoxicity has been linked to alterations in bile acid biosynthesis in mice." (PMID 21901081, 2011).
colorectal tumors (5 papers, 2013 to 2025). "The analysis revealed that tumors harboring ESR1 mutations exhibited significantly elevated transcriptional activity of ESR1, while colorectal tumors carrying TCF7L2 mutations showed decreased transcriptional activity of TCF7L2." (PMID 41390696, 2025). "Furthermore, evaluation of the ESR1 methylation status uncovered that significant methylation of this gene occurred in patients with CRC and is associated with markedly diminished ESR1 expression in colorectal tumors examined." (PMID 29568567, 2018).